HIF1A (hypoxia inducible factor 1 subunit alpha)
Diseases named in the same sentence as HIF1A in open-access papers (continued):
Sharing a sentence is not in itself a finding about the gene and the disease.
cancer (continued). "Of note, several studies have demonstrated that elevated expression of HIF-1α promoted the dedifferentiation of cancer cells into CSCs, whereas hypoxia is directly associated with poorer prognoses in patients with OS." (PMID 36555795, 2022). "Several studies have revealed the association between HIF-1α overexpression and worse prognosis in patients with this type of cancer." (PMID 36678382, 2022). "In fact, in VHL-deficient tumors, HIF-1α protein level keeps at very high level, which is considered to be a major cause of cancer progression." (PMID 35732631, 2022). "In hypoxia, WT adipocytes had a significantly higher transfer of lipids towards cancer cells compared to HIF1α-deficient adipocytes." (PMID 36329893, 2022). "Increased levels of both HIF-1 and its subunit HIF-1α are associated with the survival of cancer cells residing in the center of large and solid tumors, where they experience hypoxic or even anoxic conditions." (PMID 35163310, 2022). "In recent years, a study also reviewed the association of HIF1A 1772 C/T and 1790 G/A polymorphisms with different types of cancers and found that both polymorphisms are significantly associated with overall cancers." (PMID 35972942, 2022). "The pooled effect was calculated to evaluate the association between HIF-1α expression and clinicopathological features and overall survival in cancer patients." (PMID 35845307, 2022). "Radiation therapy against cancer cells often causes radiation resistance via accumulation of hypoxia-inducible factor 1 subunit alpha (HIF-1α) under hypoxic conditions and severe side effects." (PMID 35743281, 2022). "To estimate the association between HIF1α expression and TME in the pan-cancer dataset, we further investigated the relationship between HIF1α expression and two major types of immune regulators." (PMID 35860430, 2022). "Hypoxia is known to be involved in fibroblast reprogramming to cancer-associated fibroblasts (CAFs) via HIF-1α pathways." (PMID 36340042, 2022). "Many researchers have reported the importance of an accumulation of HIF-1α in clinical cancer tissues, causing radiation resistance, cancer aggressiveness, and poor prognosis." (PMID 35743281, 2022). "HIF-1α changes are associated with the outcomes of patients with various cancers, suggesting its critical role in carcinogenesis." (PMID 35310917, 2022). "HIF-1α-targeted genes are most significantly associated with metabolism of carbohydrates, diabetes pathways, pathways in cancer, and integration of energy metabolism." (PMID 36277475, 2022). "mTOR-dependent expression of hypoxia inducible factor 1 α (HIF1-α) was also linked to proliferation and cancer cell survival under hypoxic conditions." (PMID 36230484, 2022). "Lowering the oxygen level in cancer cells not only causes HIF-1α gene over expression but also influences the fluctuation of cellular metabolic homeostasis." (PMID 36014432, 2022). "In malignant tumors, HIF-1α is associated with oncogenic angiogenesis, proliferation, invasion, metastasis, and resistance to apoptosis." (PMID 36183290, 2022). "To assess the mutation of HIF1α in pan-cancer, we conducted an in-depth study using the cBioPortal database and found that HIF1α was altered in 5% (132/2583) of pan-cancer patients." (PMID 35860430, 2022). "This stands in contrast to most cancer types, in which increased HIF-1α expression is associated with disease progression and patient mortality." (PMID 35642641, 2022). "Overall, this study highlighted the associations between hypoxia, cancer stemness, and metabolism and also provided a mechanism by which HIF1α/USP22 promote glycolysis and stemness in HCC." (PMID 36497394, 2022). "Mounting evidence has shown that HIF-1α activation induces cancer progression; hence, various clinical studies have demonstrated the association between overexpression of HIF-1α and mortality rates in many human cancer types." (PMID 35845307, 2022).
cancer (continued). "Noticeably, accumulating evidence indicates that HIF-1α has been implicated in driving EMT in cancer by regulating several key pathways, such as Twist, Snail and Forkhead box M1 (FoxM1)." (PMID 34969360, 2022). "The Cox regression analysis of the results from 33 types of cancer suggests that the expression level of HIF1α was significantly associated with OS in LIHC, LUSC, MESO, and STAD patients (p < 0.05)." (PMID 35860430, 2022). "We performed IHC analysis of HIF1α and hypoxyprobe-1 (pimonidazole derivatives), which are hypoxia markers, to quantify the hypoxia associated with the cancer cells." (PMID 36434071, 2022). "CASQ2 overexpression induced cancer‐associated fibroblast characteristics along with increased hypoxia‐inducible factor 1α (HIF1α) expression in stromal fibroblasts." (PMID 34743414, 2022). "In COAD, HIF1α expression is associated with cancer-specific death, recurrence, vascular invasion and chemoresistance." (PMID 36273131, 2022). "Loss of VHL, which causes oxygen‐independent stabilization of HIF1α, is reported to increase the predisposition to some cancers." (PMID 34779571, 2022). "HIF-1α activates the transcription of many genes that encode proteins involved in cancer angiogenesis, glucose metabolism, cell proliferation/survival, and invasion/metastasis." (PMID 35600868, 2022). "The experiments herein describe an anticancer mechanism in which heat shock protein 90 (HSP90) stabilizes HIF-1α, a master transcription factor of oxygen homeostasis that has been implicated in the survival, proliferation and malignant progression of cancers." (PMID 35408505, 2022). "This leads to pVHL (von Hippel–Lindau protein)-dependent ubiquitination and rapid proteasomal degradation of HIF-1α, which is implicated in cancer progression." (PMID 35629968, 2022). "Our scRNA-seq analyses revealed that the evolution of PINs to malignant tumors is associated with a shift in the luminal cell state initially from A to C1, followed by C1 to C2, in a process characterized by activation of HIF1A signaling." (PMID 35867798, 2022). "Several immune checkpoint proteins also increase in a HIF-1α dependent manner, which causes T cell exhaustion in cancer." (PMID 35803912, 2022). "The data demonstrated that cancer cells under SD conditions were maintained by NPHP3-associated PC formation via ROS-induced HIF-1α and ERK activation." (PMID 36498831, 2022). "RN7SL1 causes the activation of an anti-viral signaling in the cancer cell, then leading to tumor growth and therapy resistance, while exosomal HISLA causes the activation of HIF1A, which favors glycolysis and chemoresistance in the targeted cancer cells." (PMID 35076579, 2022). "HIF1A 1772 C/T (rs11549465) and 1790 G/A (rs11549467) single nucleotide polymorphisms (SNPs) have been identified in association with different types of cancers." (PMID 35972942, 2022). "HIF-1α plays a significant role in immunity pathways linked to inflammation and cancer pathogenesis." (PMID 36555323, 2022). "These metabolites play an important role in creating a favorable environment for cancer cell progression through the stabilization and accumulation of HIF-1α, which causes the cell to become hypoxic." (PMID 35592530, 2022). "In fact, elevated HIF-1α expression is also known to be associated with a poor prognosis after radiation therapy in human cancers." (PMID 36669005, 2022). "HIF-1α is closely associated with resistance to drugs, including cisplatin and trastuzumab, in several carcinomas." (PMID 35236823, 2022).
cancer (continued). "Previous studies have shown that overexpression of HIF-1A in many cancer patients is associated with poor prognosis, including GBC." (PMID 33403040, 2021). "HIF1α, in particular, is overexpressed in several types of cancers and is known to be associated with poor prognosis and decreased survival in cancer patients." (PMID 33235291, 2021). "LIM and SH3 protein 1 (LASP-1) is a direct target gene for HIF-1α, associated with actin assembly dynamics in cancer cells." (PMID 33436044, 2021). "HIF-1α has been reported in a large number of cancer types; its primary association is in an acute response with the expression of glucose transporters, glycolytic enzymes and growth factors." (PMID 34361103, 2021). "The HIF-1α unit of the protein is recurrently overexpressed in many human cancers due to genetic alteration or mutation of oncogenes." (PMID 34572488, 2021). "The remaining factors, including β-catenin, MMP7, E-cadherin, and HIF1-α, are closely associated with the formation of the cancer microenvironment." (PMID 34490089, 2021). "HIF-1α has been shown to activate hypoxia-responsive genes which are implicated in numerous aspects of tumorigenesis and cancer progression including proliferation, metabolism, angiogenesis, invasion and metastasis." (PMID 34447314, 2021). "ROS, in fact, can directly or indirectly contribute to cancer initiation and progression, leading to the activation of oncogenic transduction pathways (i.e., HIF-1α, NF-kB) or causing DNA damage." (PMID 34072471, 2021). "In cancers, lactate also causes stimulation of HIF-1α independently of hypoxia by inhibiting the hydroxylation of the proline of HIF-1α." (PMID 34771718, 2021). "It is well known that HIF1‐α expression is strongly associated with an aggressive phenotype of cancer that includes metastasis and chemoresistance." (PMID 33773069, 2021). "HIF-1α is a cancer hallmark that accelerates survival and proliferation under abnormal glucose metabolism." (PMID 33836774, 2021). "By showing that echinomycin simultaneously causing proteasomal degradation of MYC and HIF1α, our data provided a new approach to target these and potentially other oncogenic proteins for cancer therapy." (PMID 33572152, 2021). "In agreement with our findings, HIF-1α expression has been associated with cancer cell stemness, progression, resistance, and poor prognosis." (PMID 34298771, 2021). "Many factors such as glycolytic enzymes and hypoxia-inducible factor-1α (HIF-1α) are known to be responsible for causing cancer." (PMID 34447314, 2021). "Curiously, all previously published data on the analysis of the missense mutations linked to cancers were limited to the bHLH-PAS domains of the selected bHLH-PAS members (Hif-1α and Hif-2α)." (PMID 33799876, 2021). "As a central player of intratumoral hypoxia, HIF-1α has been associated with shorter time to biochemical recurrence, metastasis, and chemoresistance in PC patients, being an attractive target for cancer therapy." (PMID 33937322, 2021). "Inflammation and cancer is frequently associated with hypoxia-mediated activation of the HIF-1α signaling pathway." (PMID 34016957, 2021). "Conversely, in advanced malignancies, expression of a module of HIF1A targets involved in collagen remodeling is associated with poor prognosis across diverse cancer types." (PMID 33654095, 2021). "In this sense, the decrease in IDH favors an increase in the stability of HIF-1α, allowing the expression of its target genes involved in glycolytic metabolism, a hallmark of cancer." (PMID 33809480, 2021). "Dysregulated growth factor signaling, activation of HIF-1α-transcription, activation of oncogenes or loss-of-function of suppressor genes contributes to cancer metabolic reprogramming." (PMID 33832535, 2021). "Under hypoxic conditions loss of Sirt3 increases tumorigenesis in cancer cells in a ROS-dependent manner by the activation of by HIF-1α." (PMID 33922139, 2021).
cancer (continued). "The overexpression of HIF1α in cancer is implicated not only in promoting cell survival but also in cell migration." (PMID 34686682, 2021). "The increased enzymatic activity of LDHB, restoration of the TCA cycle, and suppression of oncogenes via HIF-1α degradation contribute to the loss of malignancy in cancer cells while posing challenges for adaptation to hypoxia." (PMID 33806179, 2021). "A number of other studies have been performed on adaptations to hypoxia in HIF-1α deficient cancer cells." (PMID 34572020, 2021). "It is worth noting that the KRAS mutation is also associated with the upregulation of HIF-1α and the Warburg effect in cancer cells." (PMID 34540683, 2021). "These phenomena facilitated the restoration of the TCA cycle, which then inhibited the expression of hypoxia-associated genes, such as HIF-1α, and ultimately, abrogated cancer-specific metabolism under hypoxic conditions." (PMID 33806179, 2021). "HIF1α overexpression has been detected in solid tumors and is associated with the progression of a variety of cancers, including ovarian cancer, breast cancer, non-small cell lung cancer and pancreatic cancer." (PMID 34221996, 2021). "Deregulated HIF-1α signaling has been associated with several pathological conditions including cancers and brain- and muscle-disorders." (PMID 34680087, 2021). "Further, kamebakaurin causes downregulation of HIF-1α and its target gene levels, impairing cancer progression in vitro and in vivo." (PMID 34575983, 2021). "GLUT1 was reported as a prognostic gene in CRC29, and our results suggest that HNF1A plays an important role in cancer glucose metabolism in association with HIF1A." (PMID 33990627, 2021). "HIF-1α-induced expression of LOX typically causes stiffening of the ECM in cancer, thereby allowing cancer cells to easily metastasize." (PMID 34583752, 2021). "HIF-1α signaling has been implicated in several mechanisms of chemoresistance, particularly enrichment in a cancer stem cell-like phenotype." (PMID 34771673, 2021). "Consistent with our results, IGF-1/IGF-1R signaling was reported to be associated with Hif-1α or Hif-2α expression in cancers and in cells of somatic lineage." (PMID 34381769, 2021). "HIF1α induction in response to hypoxia is a well-established hallmark of cancer cell responses to stress, driving the transcription of factors essential for cell survival and ultimately dissemination under low oxygen conditions." (PMID 33603169, 2021). "VHL can inhibit the transcriptional function of HIF1α to glucose metabolism associated genes in various cancers especially renal cancer." (PMID 35006464, 2021). "Inhibition of MDH2 restrains mitochondrial respiration and causes a reduction in oxygen consumption, thus stimulating HIF-1α degradation in cancer cells." (PMID 33637686, 2021). "Depletion of NPM1 or disruption of its association with HIF‐1α selectively curtails the ability of cancer cells to survive under low oxygen." (PMID 34388291, 2021). "HIF1α causes a shift of cancer cell metabolism to glycolic pathway by upregulation of glucose transporters GLUT1 and 3, glycolytic enzymes (HK, ALDO, ENO, etc.), and enzymes involved in lactate production and lactate/proton elimination (LDH-A, MCT4, and CA9)." (PMID 34950592, 2021). "The ROS-regulated gene, hypoxia-inducible factors (HIF-1α) regulates hypoxia-associated genes, some of which are associated with the Warburg effect and its accompanying pathways and hence, are a target of cancer therapies." (PMID 33922139, 2021). "Certain polymorphisms in the HIF-1α gene have been linked to an individual's predisposition to cancers." (PMID 34256803, 2021). "In concert, silencing of NPM1 expression or disruption of its association with HIF‐1α inhibits metabolic adaptation of cancer cells and triggers apoptotic death upon hypoxia." (PMID 34388291, 2021).
cancer (continued). "Detached cancer cells gather together to cause the hypoxic environment that promotes HIF1α mediated mitophagy, removing damaged mitochondria, supporting glycolysis, which promotes cancer cell progression." (PMID 33824273, 2021). "Balanophorin B deserves further investigation to explore signaling pathways associated with HIF-1α regulation and to uncover other mechanisms by which balanophorin B exerts anti-cancer activity." (PMID 34575983, 2021). "Upregulation of carbonic anhydrase IX (CAIX) is induced through UPRmt through transcription of HIF-1α, thereby increasing high-risk carcinoma proliferation, metastasis, and locoregional failure." (PMID 34717757, 2021). "HIF-1A, which mediates adaptive responses to hypoxia, has been implicated in the induction of biological radioresistance in cancer cells under oxygen deprivation." (PMID 33604288, 2020). "Here, we evaluated the association between all identified SNPs (rs11549465, rs11549467 and rs2057482) in HIF-1α and the overall risk of cancer in all case-control studies published before April 2020." (PMID 33154192, 2020). "This response maintains cellular homeostasis, yet dysregulation of the HIF1α pathway and its downstream signaling have been reported in several pathogenic conditions that are characterized by hypoxia ranging from infection to cancer." (PMID 31935962, 2020). "Isoflurane is associated with higher levels of HIF-1α and increased proliferation and migration of cancer cells." (PMID 32863874, 2020). "In our observation, Hif-1α signaling was found to be associated with the anti-cancer mechanisms of SA, as revealed by KEGG pathway-enrichment analysis." (PMID 33381039, 2020). "The hypoxia, generated also by high oxygen consumption of cancer and endothelial cells, sustains acidosis through up-regulation of glycolytic pathway mostly linked to the stabilization of HIF-1α, the principal inductor of aerobic glycolysis in cancer." (PMID 32528879, 2020). "Further studies with functional evaluations are required to confirm the biological mechanisms underlying the role of HIF-1α SNPs in cancer development and progression." (PMID 33154192, 2020). "Mutations in SDH or fumarase in cancer lead to stabilization of hypoxia-inducible factor 1-alpha (HIF1α) and thus activate a pseudo-hypoxic response." (PMID 33199523, 2020). "Akt/mTOR signaling is closely linked to HIF-1α expression in the context of immunometabolic regulation during infection, and cancer-related aerobic glycolysis and tumor progression." (PMID 33262773, 2020). "Other enzymes (IDH1 and IDH2), when mutated, can also affect the activity of HIF-1α subunits by accumulating 2-hydroxyglutarate, a product of the conversion of α-ketoglutarate, mainly taking place in cancer cells." (PMID 32369553, 2020). "Constitutively activated HIF-1α in cancer cells is associated with an upregulated of GLUT-1 and GLUT-3 expression." (PMID 32806533, 2020). "In this review, two studies reported a close association between the presence of “cancer cell-lined vessels”, or VM, and hypoxia-inducible factor-1 alpha (HIF-1α) in OSCC and ESCC." (PMID 32102317, 2020). "HIF-1α is activated in cancer cells by the loss of function of tumor suppressors (e.g., VHL or PTEN) and/or oncogene gain of function (constitutive growth factor /receptor activation." (PMID 32354000, 2020). "Increasing evidence confirmed that HIF-1α is associated with the development and progression of multiple human cancers." (PMID 33154192, 2020).